IL6 (interleukin 6)
Diseases named in the same sentence as IL6 in open-access papers (continued):
Sharing a sentence is not in itself a finding about the gene and the disease.
cancer (continued). "As IL-6 has a multi-factorial role in promoting cancer cell proliferation, metastasis, and cancer stem cell induction, we investigated in vitro the potential efficacy of neutralizing MSL TNBC autocrine IL-6 production in combination with docetaxel treatment." (PMID 35260569, 2022). "Presently, an abundant amount of evidence has indicated that STAT3, as well as cytokine IL6 and IL8, potentially form a positive feedback loop in cancer patients while enhancing cisplatin resistance." (PMID 36292923, 2022). "Many macrophages-derived cytokines present in the TME have already been verified to affect the response of cancer cells to chemotherapy like CCL2, CCL22, IL-6 and CCL18." (PMID 36151545, 2022). "Another study showed that the expression of protein phosphatase of regenerating liver-3 (PRL-3) in CRC cells was able to activate the MAPK pathway in TAMs, thus leading to the release of IL-6 and IL-8 and inducing the EMT in cancer cells." (PMID 36555840, 2022). "Significant correlations between IL6 and EMT/CSCs have also been widely identified in other cancer types." (PMID 34991668, 2022). "Application was also found to inhibit CSC markers, to modulate EMT markers, and to activate IL-6/STAT3 signalling, directly decreasing cancer cell invasiveness and migration." (PMID 35276890, 2022). "Many proteins (e.g., Interleukin-6 (IL-6) and YKL-40/chitinase 3-like 1 protein (CHI3L1)) secreted by cancer cells, macrophages, neutrophils, and fibroblasts stimulate inflammation." (PMID 35335885, 2022). "SHH binds to the PTCH1 receptor expressed on the cell membrane of osteoblasts and cancer cells, to activate the SHH/PTCH1/GLI1 signaling pathway, which leads to the binding of GLI1 to the promoter of IL-6 and increases the IL-6 expression." (PMID 35285760, 2022). "Blocking IL-6 or IFN-γ, respectively, alleviated the cachectic phenotype in mice models where cancer cell lines overexpressed it." (PMID 35159388, 2022). "The IL-6/JAK/STAT3 signaling has been shown to drive the proliferation, survival, invasiveness, and metastasis of cancer cells, while suppressing the antitumor immune response." (PMID 35102139, 2022). "First, the GSEA analysis revealed that CASZ1 overexpression was related to cancer‐related signaling pathways, including the “Notch signaling,” “transforming growth factor‐beta (TGF‐β) signaling,” “IL6_JAK_STAT3 signaling,” and “EMT signaling”." (PMID 36276925, 2022). "TME cells secrete a variety of pro-inflammatory cytokines that interfere with anti-cancer immune response (VEGF), interleukins (IL-6, IL-12), epidermal growth factor (EGF), as well as tumor necrosis factor-alpha (TNF-a) and indoleamine-2,3-dioxygenase (IDO)." (PMID 35743107, 2022). "It is possible that clinical trials based on elevated biomarker levels (such as IL-1β, IL-6, or TNF) in each individual patient will allow a more targeted approach to ameliorating cancer cachexia." (PMID 36358681, 2022). "In cancer cachexia, various cytokines, such as TNF-α and IL-6, promote the lipolysis of triglycerides in WAT." (PMID 36072935, 2022). "As such, while other studies have found that IL-6, IL-1b, and CRP is significantly up-regulated in specific groups of cancer patients exhibiting poor sleep, this/these biomarker(s) did not correlate significantly with sleep quality in our broader cohort." (PMID 36213755, 2022). "GSVA analysis demonstrated that some representative cancer pathways are closely related to AC010973.2, including E2F target, IL6-JAK-STAT3 signaling, apoptosis signaling, hypoxia signaling, and fatty acid metabolism." (PMID 35277527, 2022). "In CRC cells, IL-6 induced Cyclin D1 expression, and in 3D CRC spheroids stimulated the expansion of cancer stem cells." (PMID 35625868, 2022).
cancer (continued). "For example, extracellular HMGB1 stimulates the release of pro-inflammatory cytokines such as IL-6 and IL-8 by triggering MAPK- and MyD88-dependent NF-κB pathways, subsequently facilitating cancer cell proliferation, angiogenesis, EMT, invasion and metastasis." (PMID 35927755, 2022). "Particularly, IL-6 can promote metastasis by aberrantly activating the STAT3 pathway, supporting cancer stem cells (CSC)." (PMID 35269666, 2022). "As already mentioned, STAT3 is influenced by the activity of IL-6 and IL-8, and studies show that these interleukins contribute to the induction of EMT in cancer cells in vitro." (PMID 36232388, 2022). "Subsequently, IL1-β secreted by TAMs stabilizes intracellular β-catenin potentiating Wnt signaling in cancer cells via NFkB/PDK1 and glycogen synthase kinase 3-beta (GSK3β) inhibition, whereas IL-6 further amplifies inflammation within the TME." (PMID 36613445, 2022). "In contrast, blocking individual cytokines (IGFBP-3, IGFBP-2, VEGF, PDGF-AA, IL-6 or IL-31) in A549-fibrocyte co-culture CM using neutralizing antibodies decreased ET1 and ETA on cancer cells." (PMID 36241617, 2022). "IL-6 signaling (mainly via the JAK/STAT3 signaling pathway in epithelial and immune cells) can promote chronic inflammation and cancer development (Johnson, O'Keefe and Grandis 2018)." (PMID 36313280, 2022). "It has been demonstrated that IL-6 contributes to the accumulation and activation of MDSC in cancer." (PMID 36263056, 2022). "Therefore, we detected the mRNA expression in renal tissue and found that only Il-6 mRNA expression levels did not significantly upregulate in XBP1cKO UIRI group compared to XBP1fl/fl UIRI group, which could be explained that XBP1s can activate IL-6 mRNA transcription in cancer cell." (PMID 35765067, 2022). "Another antitumor property of QC is its ability to inhibit inflammatory mediators including IFN-γ, IL-6, COX-2, IL-8, iNOS, TNF-α, and many other cancer inflammatory mechanisms." (PMID 36233051, 2022). "Cytokines such as MIF, IL-6, and TGF-β used as adjuvants in cancer treatment has been extensively investigated in many clinical studies." (PMID 36313280, 2022). "This determinant of T cell function predicts that the presence of pro-inflammatory mediators, including IL-6, CRP, and other factors, inhibits T cell effector function and culminates in poor clinical outcomes in many cancers." (PMID 35359426, 2022). "Systemic inflammation too plays a role in the progression of cancer cachexia: proinflammatory cytokines, such as IL-6 or TNF-α, are elevated in some cachectic patients’ plasma and cancer-bearing models." (PMID 35406586, 2022). "NETs enhance the expression of EMT markers ZEB1, Snail and fibronectin, cancer stem cell marker CD44, proinflammatory mediators, such as IL1β, IL6, IL8, CXCR1, MMP2 and MMP9." (PMID 35574410, 2022). "In humans, phase I and II trials on cancer patients with ALD518, a humanized IL-6 antibody developed to treat cachexia was found to be safe and well tolerated." (PMID 36077789, 2022). "Preclinical studies have shown that anti-inflammatory agents targeting cytokines, such as TNF-α, IL-6, IL-8, IL-22, and IFN-γ, demonstrate protective effects against various types of cancer." (PMID 35799889, 2022). "Activation of interleukin-6 (IL6) and epidermal growth factor receptor (EGFR) pathways, and key genes in cancer-related glucose metabolic reprogramming, were validated in TAA-CCAs." (PMID 35619118, 2022). "The interactions between immune cells, cancer cells, necrotic cells, and adipocytes result in interesting dynamics and lead to the secretion of important cytokines such as HMGB1, IL12, IL10, and IL6." (PMID 35294447, 2022). "Indeed, IL-6 is associated with aggressive PCa phenotypes and may be involved in the metastatic process via the regulation of epithelial-mesenchymal transition (EMT) and the homing of cancer cells to the bone." (PMID 35406450, 2022).
cancer (continued). "The chemokines secreted by astrocytes, such as IL-6 and TGF-β, can also function as prooncogenic triggers for cancer cells, thus promoting the further migration and invasion of cancer cells." (PMID 35203510, 2022). "Chanling Gao exerted the analgesic effects in the cancer-induced bone pain (CIBP) rat model by inhibiting the IKKβ/NF-κB signaling pathway and the synthesis and release of TNF-α, IL-1β, and IL6." (PMID 36415861, 2022). "In this concern, the IL-6 signaling cascade was shown to inhibit the expression of major MHC-II and CD86 molecules on the surfaces of DCs in vivo, resulting in the delay of cancer-related antigen presentation." (PMID 36405719, 2022). "It has long been recognized that IL-6 can activate STAT3 which is closely related to the occurrence, development, and metastasis of malignant tumors during HP infection." (PMID 35958524, 2022). "Therapy with CGDCM resulted in a decrease in IL-6 and TNF-α expression, implying that the inflammatory signaling cascade is suppressed, slowing cancer progression." (PMID 35840761, 2022). "However, the similar responsiveness of SM and LV fibroblasts related to NLRP3 activation following IL-6 suggests that SM-derived fibroblasts could be potentially used as a tool to mirror the cardiac inflammatory NLRP3 response during cancer progression prior to cardiac damage." (PMID 35967380, 2022). "Of the EMT pathway, the genes IL-6, SFRP4, FZD8, ADAM12, and CCN2 are known to promote cancer cell invasion and migration in multiple types of cancers." (PMID 35505422, 2022). "Our experimental approach exploits the paracrine up-regulation of CCL2, CCL5, IL-1β, and IL-6 in ADMSC in response to TNBC cells secretome, confirming and complementing prior co-culture approaches mixing cancer cells and adipocytes." (PMID 35268073, 2022). "IL-6 is a well-established inducer of STAT3 signaling, and STAT3 signaling mediates cancer proliferation." (PMID 35260569, 2022). "Clinically, the increase in IL-6 and IL-10 on PTX administration is correlated with joint pain and fatigue respectively in cancer patients." (PMID 35273508, 2022). "Molecular docking of compounds 4 and 6, the cancer-inducing agent NDEA, and the standard sorafenib was performed on the targeted proteins, namely MDM2, TNF-α, TGF-β, FAK, and IL-6." (PMID 35661799, 2022). "Our aim was to evaluate concentrations of IL‐6 and TPO in dogs with carcinoma with respect to their platelet count, and to compare the findings to those in normal, healthy dogs." (PMID 34881459, 2022). "Apart from miR-382, STAT3 was also regulated by miR-1246, IL-6, IL-10, nuclear factor kappa-B p65, or ERK and promoted M2-type macrophages in the progression of carcinoma." (PMID 35585990, 2022). "EVs secreted by cancer cells contain pro-angiogenic mediators, including vascular endothelial growth factor (VEGFA), interleukin-8 (IL-8), interleukin 6 (IL-6) and fibroblast growth factor 2 (FGF2)." (PMID 34283059, 2021). "In the present study, we also observed that the pro-inflammatory cytokines that promote cancer progression, namely, IFN-γ, TNF-α, IL-1β, IL-6, IL-8, and IL-12, were decreased." (PMID 33869169, 2021). "Previous cumulative studies have found that increased expression of IL-6 stimulates overactivation of JAK/STAT3 signals and leads to poor prognosis in cancer patients." (PMID 34745261, 2021). "Paget postulated that various cytokines secreted from cancer cells, including CCL2, CCL5, and interleukin-6, and a specific microenvironment communicates to attract cancer cells toward specific organs." (PMID 33806911, 2021). "In summary, our results demonstrated that MMP-2 plays a major role in cancer progression for its ability to degrade ECM components, and that its expression and activity are up-regulated through IL-6 in T88 and T93 cells." (PMID 34885656, 2021).
cancer (continued). "Chemoattractants such as CCL2 (or MCP1), secreted by cancer cells, can stimulate microglia via CCR2 activation, and recruit the microglia to the tumor microenvironment to support invasiveness through IL-6 expression." (PMID 34566949, 2021). "IL-6/JAK/STAT pathway is aberrantly hyper-activated in many types of cancer including ccRCC and plays a significant part in the progression of cancer cachexia through regulating the inflammatory response." (PMID 33686949, 2021). "IL6 and TNF α are inflammatory cytokines that also have direct cytotoxic effects on cancer cell lines and are able to recruit immune cells." (PMID 34944584, 2021). "Results reveal that MMP9 and IL-6 secretion was significantly upregulated in response to all cancer EVs, relative to untreated cells, while the amount of MMP9 or IL-6 induced was dependent on the cancer cell secreting the EVs." (PMID 33984826, 2021). "To the best of our knowledge, we firstly described considerable elevation of IL-6, IL-8, TNF-α, IP-10, HCC-1, and PF-4 levels in OSCC compared to OL patients, being detectable from early cancer stages." (PMID 33924500, 2021). "Certainly, BZA acts as a GP130 inhibitor by competing with IL-6 or IL-11 for the interaction of GP130, leading to the deactivation of IL-6/GP130 signaling and delayed cancer progression." (PMID 34948224, 2021). "The expression profile of inflammation- and cancer-related genes (IL-1β, IL-8, TNF-α, IFN-γ, IL-6, NF-κB, and IL-13) were measured using qPCR." (PMID 37901256, 2021). "CAFs secrete pro-inflammatory cytokines (e.g., COX-2, CXL1, CCL5, CXC11 and IL-6) that induce EMT, cancer cell proliferation, invasion, chemoresistance and inhibit cancer cell apoptosis." (PMID 34830897, 2021). "This aligns with the literature supporting that IL-6 and its activation of STAT3 counteracts the effects of radio- and chemotherapy in many cancers." (PMID 35087822, 2021). "We found that the GM-CSF growth factor, and the cytokines GRO a/b/g, GRO α, IL-6, IL-8 and RANTES were markedly increased in LC5-cancer cell cocultures compared to LC5 monoculture." (PMID 33807441, 2021). "Macrophages differentiate into the M2 type when stimulated with interleukin 6 (IL6), macrophage colony stimulating factor (M-CSF), and PGE2 secreted by cancer cells." (PMID 34135469, 2021). "Another study showed that IL-6/JAK/STAT3 and TGF-β/SMAD pathways are required for the epithelial–mesenchymal transition in the early stages of cancer." (PMID 34771727, 2021). "The inducible factors that drove monocyte differentiation into pro-invasive TAM were primarily characterized as CAF-derived GM-CSF and IL-6, and are known to regulate the presence of TAM and promote cancer cell invasion and metastasis." (PMID 34094963, 2021). "This IL-6 expression was dependant on TG2 upregulated through NF-kB, PI3K-, and JNK-dependent signalling cascades in promoting a cancer stem cell phenotype and inducing the EMT and metastasis when amplified by Interleukin 1 beta (IL1B) production." (PMID 34205140, 2021). "Other cytokines, specifically IL-6 and OSM, clearly have more profound effects in cancer through STAT3—this has left LIF in the proverbial wayside, as more potent activators of STAT3 have been targeted for study." (PMID 34395259, 2021). "Many proteins (e.g., Interleukin-6 (IL-6) and YKL-40/CHI3L1) secreted by cancer cells, macrophages, neutrophils and fibroblasts stimulate inflammation." (PMID 34200156, 2021). "Moreover, IL-6 may induce proliferation and prolong cancer cells’ survival." (PMID 33923108, 2021). "For instance, IL-6, a well-known protumorigenic SASP in various types of cancer, sometimes acts as an antitumorigenic SASP recruiting antitumor immune cells to the tumor tissue." (PMID 34916607, 2021).
cancer (continued). "In contrast, gallic acid equivalent (GAE) treatment increased intracellular ROS production in human cancer colon fibroblast cells and decreased the expression levels of TNF-α, IL-1β, IL-6, and NF-κB to suppress cell proliferation." (PMID 33664749, 2021). "To investigate their sub-exosomal localization, we added recombinant human or mouse CCL2 and IL-6, both cytokines present in both plasma exosome isolates and TIF, to two human and two murine cancer cell line-derived exosomes." (PMID 34112803, 2021). "Interleukin-6 (IL-6) and TNF-α play major roles in cancer proliferation by regulating cell growth and metabolism." (PMID 34944574, 2021). "The collective data suggest that CD10 in CAFs sustains cancer stemness and chemoresistance via a GPR77/IL‐6/IL‐8 independent pathway." (PMID 34363355, 2021). "Several inflammatory mediators, such as TNF-α, IL-6, TGF-β, and IL-10, have been shown to play a role in cancer progression." (PMID 34485118, 2021). "The positive feedback loop demonstrated here suggests that IL-6/STAT3 play critical roles in the initiation and promotion of cancer metastasis." (PMID 33500736, 2021). "PM-induced oxidative stress has been accepted as a key molecular mechanism of many inflammatory modulators, such as tumor necrosis factor-α (TNF-α), interleukins IL-1, IL-6, IL-8, and COX-2, including MMP-9 expression and cancer cell metastasis." (PMID 34439757, 2021). "Although most of the evidence is derived from studies performed in cancer cell lines, the pro-EMT and pro-invasive effects of IL-6 and OSM have been proved in vivo in animal models of breast, lung, gastric, cervical and head and neck cancers, among others." (PMID 34361105, 2021). "The clinical significance of lower IL-6 and CRP levels and higher ferritin levels following corticosteroid use in cancer patients also requires further inquiry." (PMID 33649382, 2021). "Additionally, the increased production of pro-inflammatory cytokines such as IL-1b, IL-6, IFNa2, and TNFa, amongst others, is critical to the development of the host response to foreign microorganisms, the vaccine-based immune response, and the response to cancer immunotherapy." (PMID 33807734, 2021). "These cells produce pro-inflammatory adipokines, such as IL-6 and CCL7 which favor cancer progression." (PMID 34063828, 2021). "As such, IL-6 production results in autocrine and paracrine activation of STAT3 signaling that promotes survival of cancer cells in response to DNA damage and pro-apoptotic mediators such as TNFα." (PMID 35087822, 2021). "NuF can inhibiting IL-6 and TGF-β trigger EMT that influences the HIF-1α activity for inhibiting cancer progression during Iressa therapy." (PMID 34064322, 2021). "Serum YKL-40, IL6, and CRP were found to be elevated in advanced-stage cancer patients with poor performance statuses." (PMID 34579512, 2021). "When more SP is released, it can decrease the apoptosis subsequently by modulating the immune markers IL4, IL6, and IL10, resulting in unrestrained cell division, cell progression, and prominent cancer metastasis." (PMID 34692834, 2021). "Inflammatory factors such as interleukin-6 (IL-6), tumor necrosis factor (TNF)-α, and leukemia inhibitory factor (LIF) are commonly examined for their roles in cancer-induced muscle wasting." (PMID 34395422, 2021). "They impact on cancer metastasis through releasing soluble factors such as chemokine SDF-1, IL-6 and CCL5." (PMID 33838662, 2021). "Multiple studies have demonstrated that IL-6-mediated EMP and stemness provide resistance to conventional chemo(radio)therapy in different cancer types and even to targeted therapy, such as trastuzumab or tyrosine kinase inhibitors (TKIs)." (PMID 34361105, 2021). "Furthermore, these synthesized compounds can inhibit epidermal growth factor receptor (EGFR) (IC50: 0.24 μM), proto-oncogene tyrosine-protein kinase (Src) (IC50: 0.96 μM), and interleukin-6 (IL-6) (% of control: 20%) and might play anticancer roles in various cancers." (PMID 34208562, 2021).